HCFC1R1 (host cell factor C1 regulator 1)
Description:
Regulates HCFC1 activity by modulating its subcellular localization. Overexpression of HCFC1R1 leads to accumulation of HCFC1 in the cytoplasm. HCFC1R1-mediated export may provide the pool of cytoplasmic HCFC1 required for import of virion-derived VP16 into the nucleus.
Synonyms: HPIP; FLJ20568
Tractability: No criterion of Open Targets' tractability assessment is met for any kind of drug.
Gene: Protein-coding gene on chromosome 16 (3,022,625 to 3,024,286, reverse strand). Ensembl gene ENSG00000103145.
Subcellular location: Cytoplasm; Nucleus
Subcellular location (Human Protein Atlas): Nucleoplasm
Gene Ontology:
Cellular component: cytoplasm; nucleus
Genetic constraint (gnomAD): Loss-of-function variants: 18 observed, 13.01 expected, observed/expected ratio (o/e) 1.38, 90% interval 0.95 to 1.88. The synonymous counts are far from expectation, so gnomAD's model fits this gene poorly and the ratio says little. Missense variants: 218 observed, 157.87 expected, observed/expected ratio (o/e) 1.38, 90% interval 1.24 to 1.54. Synonymous variants: 87 observed, 63.27 expected, observed/expected ratio (o/e) 1.38, 90% interval 1.15 to 1.64.
Homologues: Orthologues: chimpanzee HCFC1R1 (100% identical), pig HCFC1R1 (86% identical), dog HCFC1R1 (83% identical), mouse Hcfc1r1 (72% identical), rat Hcfc1r1 (70% identical), rabbit HCFC1R1 (60% identical).
Diseases named in the same sentence as HCFC1R1 in open-access papers:
HCFC1R1 is named in the same sentence as 2 diseases in open-access papers, as found by Europe PMC text mining. Sharing a sentence is not in itself a finding about the gene and the disease.
HCFC1R1 shares sentences with these, for which no sentence is quoted: infection (1 paper); uterine serous carcinoma (1).